CCR2 (C-C motif chemokine receptor 2)
Diseases named in the same sentence as CCR2 in open-access papers (continued):
Sharing a sentence is not in itself a finding about the gene and the disease.
Obesity (continued). "In many preclinical models of diet induced obesity and microvascular disease genetic deletion or pharmacological inhibition of CCR2 dramatically reduces macrophage recruitment and protects the kidney from functional decline." (PMID 32608058, 2020). "Earlier studies in humans and mice demonstrated that obesity is associated with an expansion of VAT DCs, mainly cDCs that accumulate in the VAT in a CCR7-dependent and CCR2-independent manner." (PMID 32499756, 2020). "In this study, we investigated the therapeutic effect of CCR2 KO on obesity-induced kidney damage including renal function and glomerular structure." (PMID 31498850, 2019). "We investigated the therapeutic effects and the mechanism of CCL2/CCR2 signaling in obesity-induced kidney injury." (PMID 31498850, 2019). "Macrophages are recruited to adipose tissue in part via CCR2 interaction with CCL2 that is upregulated in obesity." (PMID 30254630, 2018). "For instance, adipose tissue macrophages from CCR2 knockout mice are polarized to the M2-like macrophages, even after obesity and CCR2 knockout mice were found to be protected from diet-induced insulin resistance." (PMID 29507865, 2018). "This study provides experimental evidence that early CCR2 intervention attenuates adipose tissue inflammation in obesity and subsequent NASH development." (PMID 28076416, 2017). "In the adipose tissue, increased CCL2 signaling through its receptor, CCR2, links obesity and insulin resistance through the induction of an inflammatory response." (PMID 27832159, 2016). "Certain functions of CCR2 have been revealed when it binds CCL2 forming CCL2/CCR2 axis, involving formation of atherosclerotic plaques, insulin resistance in obesity, and inflammatory responses against tumors." (PMID 26701209, 2016). "The effects of MCP-1 in recruiting monocytes, T lymphocytes and natural killer cells are dependent of the C-C motif chemokine receptor (CCR2), since the use of a specific antagonist for this receptor attenuates obesity-induced macrophage accumulation." (PMID 26578976, 2015). "The interaction of MCP-1 with its receptor, CCR2, is considered pivotal for the recruitment of ATMs and the development of obesity-induced insulin resistance." (PMID 26197341, 2015). "We have recently shown that obesity and diabetes are associated with an increase in the expression of IL-4, LIGHT, CCR-2, and MMP-9 in MNC and that, following gastric bypass surgery, there is a reduction in the expression of these genes." (PMID 25642424, 2015). "In contrast, it has been shown that the inactivation of CCR2 inhibits NASH in the liver and that the genetic deletion of MCP-1 and CCR2 attenuates obesity and improves insulin resistance and hepatic steatosis." (PMID 26197341, 2015). "MDSC expression of the CCL2 receptor, CCR2, was unaltered by obesity but greater percentages of CCR2+ MDSCs were present in renal tumors from obese mice." (PMID 25769110, 2015). "Consistent with a central role in immune cell recruitment, CCR2 deficiency ameliorates obesity, VAT inflammation, and systemic IR; in fact, hematopoietic CCR2 deficiency is essential for improvement." (PMID 24149114, 2014). "In other experimental models characterized by abnormal inflammatory skewing of MPs such as diabetes and obesity, CCL2 or CCR2 deficiency has also been linked to a switch away from excessive proinflammatory MP polarization." (PMID 25312642, 2014). "MCP-1 and its receptor CCR2 are considered to be pivotal for macrophage infiltration in adipose tissue in obesity." (PMID 23637889, 2013). "First, an intact CCL2/CCR2 axis, the principal chemotactic pathway, is necessary for understanding the mechanistic links between adipose tissue inflammation and the effects of obesity." (PMID 20936118, 2010). "Furthermore, MCP-1 and CCR2 mediate monocyte recruitment to white adipose tissue, promoting inflammation and insulin resistance in obesity." (PMID 41171725, 2025).
Obesity (continued). "Moreover, the involvement of CCR2 and CCR5 has been shown in preclinical models of obesity-induced hypersensitivity and diabetic neuropathy, where administration of dual CCR2/CCR5 antagonists led to pain reduction." (PMID 41301743, 2025). "In addition to other antagonists, specific CCR2 antagonists have shown efficacy in reducing blood glucose and enhancing insulin sensitivity in obesity treatments." (PMID 39334887, 2024). "Pro-inflammatory chemokines could potentially serve as diagnostic or prognostic biomarkers in the context of obesity and its complications, and potential chemokine inhibitors (including MCP-1 or the CCR2) could represent a new class of drugs." (PMID 39275140, 2024). "CCL2, a member of the CC chemokine family, is a key factor in obesity-induced inflammation, as it attracts CCR2-expressing monocytes and favors their differentiation into M1 macrophages, which promote adipogenesis and increase the accumulation of adipose tissue." (PMID 39457105, 2024). "Together, our data suggest that obesity leads to an increased proliferation and accumulation of pro-inflammatory CCR2+Ly6C+ monocytes/macrophages in skin wounds, which may contribute to delayed healing." (PMID 38474365, 2024). "Therefore, we assessed the effects of obesity on the accumulation of CCR2+ monocytes/macrophages throughout the healing process." (PMID 38474365, 2024). "However, another study has reported opposite results, suggesting that Caspase-1-deficient mice were more susceptible to high-fat diet-induced obesity and increased inflammation, primarily through the CCL2/C-C chemokine receptor 2 (CCR2) axis in adipose tissue." (PMID 38672517, 2024). "The CCR2+/- scRNA seq data set included subjects who were lean and with obesity (n=4/group)." (PMID 39872537, 2024). "Interestingly, ATE accumulation during obesity were dependent of a population of CCR2-expressing cell." (PMID 38567054, 2023). "The blockade of MCP-1/CCR2 signaling for inhibiting pro-inflammatory macrophage infiltration could be a promising therapeutic approach for obesity and diabetes." (PMID 35909571, 2022). "Mounting studies have demonstrated that monocyte-derived macrophages are recruited into tissues (particularly into adipose tissue) via C-C chemokine receptor type 2 (CCR2) and secrete inflammatory cytokines such as TNF-α during obesity, thereby causing systemic inflammation and insulin resistance." (PMID 35563728, 2022). "The proportion of microglia that express CCR2 also increases in obesity, which may indicate their activation, or chemoattraction toward areas with fenestrated capillaries and the gradient of increased leptin, free fatty acids, or insulin." (PMID 34154608, 2021). "The C-C chemokine receptor type 2 (CCR2) was found to be increased in obesity." (PMID 34698104, 2021). "Lee found that using CCR2 knockout mice to block CCL2-CCR2 signaling could ameliorate obesity-induced albuminuria in the kidney through blocking oxidative stress." (PMID 32185196, 2020). "Moreover, investigators showed that blocking CCL2/CCR2 signaling pathway can ameliorate renal injury and proteinuria in a mouse model of obesity and insulin resistance." (PMID 31919470, 2020). "Similar to obesity, aged ATMs display an elevated expression of the chemokine receptor CCR2, possessed enhance secretion of pro-inflammatory cytokines IL-6, MCP-1, and TNFα, and a decrease in expression of PPARγ, which mechanistically accounts for the loss in M2 ATMs." (PMID 32499756, 2020). "In addition, the chemokine monocyte chemoattractant protein-1 (MCP-1/CCL2), and its receptor C-C motif chemokine receptor 2 (CCR2) play a critical role in macrophage infiltration and insulin resistance associated with obesity." (PMID 30723473, 2019). "While genetic or pharmacologic disruption of CCR2 appears to attenuate liver inflammation with obesity this has not been consistent across CCR2 loss of function models." (PMID 32038642, 2019).
Obesity (continued). "Further understanding of the NF‐κB, TNF‐α, and CCR2 pathways could lead to effective interventions for obesity‐induced CKD." (PMID 29632818, 2018). "Further, MCP-1/CCR2-deficiency increased adiponectin expression, and improved systemic glucose homeostasis and insulin sensitivity; an effect that was mirrored by acute CCR2 antagonism in mice with established HFD-induced obesity." (PMID 29186929, 2017). "In fact, serum and liver MCP-1 levels are increased in NASH patients, whereas in animal NASH models, the genetic deletion of MCP-1 and CCR2 or the inactivation of CCR2 reduces macrophage infiltration, attenuates obesity, and improves both insulin resistance and hepatic steatosis." (PMID 28420094, 2017). "Notably, increased adipose tissue levels of multiple β-chemokines (CCL2, CCL3, CCL5, CCL7, CCL8, CCL11) and chemokine receptors (CCR1, CCR2, CCR3, CCR5) have been linked with obesity and associated metabolic inflammation." (PMID 28396851, 2017). "Similarly, obesity induces hepatic recruitment of monocytes via CCR2 promoting steatosis and insulin resistance." (PMID 28993702, 2017). "C-C motif chemokine receptor 2-knockout (Ccr2-KO) mice attributed insulin resistance in diet-induced obesity to the shift of from pro-inflammatory M1 macrophages into alternatively activated M2 macrophages and the reduction of anti-inflammatory cytokine interleukin-10 (IL-10)." (PMID 27703473, 2016). "Thus, data from our study suggest that the effect of CD47 on macrophage infiltration into adipose tissue and the development of chronic inflammation under obesity conditions is MCP1/CCR2 dependent." (PMID 25747123, 2015). "The interaction of MCP-1 with its receptor, CCR2, is considered pivotal for the recruitment of adipose tissue macrophages (ATMs) and the development of obesity-induced insulin resistance, although ATM recruitment can occur independently from MCP-1/CCR2 signaling." (PMID 26578976, 2015). "Obesity promotes the mobilization of monocytes from the bone marrow in part by activating the CCR2." (PMID 24823865, 2014). "Many of these molecules were not induced in adipose tissue macrophages from C-C chemokine receptor 2 (CCR2) knockout mice fed with a high-fat diet, supporting the importance of CCR2 in regulating recruitment of inflammatory activated macrophages during obesity." (PMID 23941259, 2013). "Also, in mice with pre-existing obesity, short-term pharmacologic antagonism of CCR2 reduces adipose tissue macrophage content and improves in vivo insulin sensitivity." (PMID 20936118, 2010). "Indeed, monocytes express abundant levels of active chemokine receptors among which CCR2 has been importantly implicated in macrophage chemoattraction to WAT, where Hp is abundantly expressed and released during obesity." (PMID 20017911, 2009). "Further, we have shown that by pharmacologically inhibiting CCR2 we could block cell migration to Hp, further strengthening the notion that drugs for the obesity-induced inflammatory state could be developed by acting on this receptor." (PMID 20017911, 2009). "Consequently, inhibiting GPR21 activity may offer a compelling approach to mitigate obesity-induced insulin resistance and CCR2-mediated inflammatory responses." (PMID 39334887, 2024). "It is worth noting that after retesting the CCR2 in these tumor tissues, we found that the expression levels of CCR2 in PCa tumor tissues also increased under obesity, which may be another positive response of tumor cells to search for CCL2 in distal bone marrow." (PMID 38221626, 2024). "Importantly, obesity increased proliferation of these pro-inflammatory Ly6C+F4/80lo/-CCR2+ monocytes/macrophages, which may contribute to the delayed healing in obese mice." (PMID 38474365, 2024). "In addition to CCL2/CCR2, other chemokines and their receptors may play a role in the increased macrophage accumulation in adipose tissue in obesity." (PMID 37153549, 2023).
Obesity (continued). "Moreover, mice with CCR2 deficiency in bone marrow cells or macrophages had lower macrophage numbers in adipose tissue after high-fat diet (HFD) feeding, indicating that CCR2 plays a crucial role in macrophage recruitment into adipose tissue during obesity." (PMID 37153549, 2023). "In addition, mice deficient in C–C chemokine receptor type 2 (Ccr2)−/ −, a chemokine receptor required for monocytes to egress from BM, are protected from obesity-associated complications but not weight gain." (PMID 38567054, 2023). "Mrc1 deficiency is associated with a decrease in circulating neutrophils and pro-inflammatory CCR2+ monocytes and low infiltration of these cells into tissues, against a background of increased presence of adipocytes in the BM in obese mice (Mrc1-/-) (slowing the development of obesity)." (PMID 37569635, 2023). "Therefore, blockade of CCL2/CCR2 signaling by CCR2 depletion might ameliorate obesity-induced albuminuria through blocking oxidative stress, ER stress, and lipid accumulation." (PMID 31498850, 2019). "However, CCR2 depletion restored these obesity-induced kidney injuries." (PMID 31498850, 2019). "Therefore, CCR2 depletion might be a novel therapeutic target against obesity-induced kidney injury." (PMID 31498850, 2019). "The human data shows that obesity enhances the activation of the FA/HIF‐1α/CCL2 pathway in tumor tissue and the CCL2/CCR2/PPARα axis in adjacent adipose tissue, thereby accelerating tumor progression and promoting adipolysis in the surrounding adipose tissue." (PMID 41160815, 2026). "Inflammatory markers, including CD16, CD11c, CCR2, CCR5, TNF-α, IL-1β, IL-2, IL-12, CCL8, CCL19, and CXCL9, were positively correlated with IL-23 in the AT-compartment in the obesity context." (PMID 41158638, 2025). "This review provides and discusses current knowledge of the involvement of CCR2, CCR5, and their ligands in diabetic neuropathy and obesity-induced hypersensitivity, emphasizing evidence from rodent-based studies." (PMID 39457105, 2024). "The contribution of MCP-1/CCR2 in obesity-induced inflammation revealed increased gene expression of CC chemokines and their receptors (such as MCP-1 and CCR2) in visceral and subcutaneous adipose tissues of obese patients compared to lean subjects." (PMID 36364860, 2022). "In the early stage of obesity, chemotactic monocyte chemoattractant protein-1 (MCP-1)/C-C chemokine receptor 2 (CCR2) are secreted by hypertrophic adipocyte, in which the cytokines promote the accumulation of macrophage in obese adipose tissue." (PMID 32265835, 2020). "However, the effects of CCR2 knockout on obesity-induced kidney injury remain unclear." (PMID 31498850, 2019). "However, the effect of CCR2 KO on obesity-induced kidney injury remains unclear." (PMID 31498850, 2019). "In summary, obesity can elevate the inflammatory cytokine, TNF‐α and CCR2, resulting in increases in albuminuria." (PMID 29632818, 2018). "The significance of MCP-1 in the pathology of obesity-induced metabolic dysfunctions has been further demonstrated in HFD-fed MCP-1−/− and CCR2−/− mice." (PMID 29186929, 2017). "Another study found that, in CCR2 knockout mouse, infiltration of macrophage in WAT due to HFD feeding-induced obesity was reduced and insulin sensitively was enhanced by comparison with wild type mice." (PMID 28168013, 2017). "The insulin resistant proinflammatory states of obesity and type 2 diabetes are characterized by an increase in IL-4, MMP-9, LIGHT, and CCR-2 expression in MNC and MMP-9 and NOM concentrations in plasma." (PMID 25642424, 2015). "In this model of HFpEF induced by a high-fat diet and L-NAME, which produced obesity, glucose intolerance, and hypertension, myocardial resident reparative CCR2−MHCII− macrophages decreased and proinflammatory CCR2+MHCII+ macrophages increased during preclinical stages." (PMID 41155489, 2025).
Obesity (continued). "There were some sex differences in the expression of monocyte activation markers: in children with obesity, expression (MFI) of CCR2, CD11b, CD11c, TLR2 and TLR4 were higher in females than males indicating that monocytes in female children with obesity have a more pro-inflammatory phenotype." (PMID 38741712, 2024). "Along with increased Ly6C+CCR2+ cells in skin wounds, we also observed elevated levels of circulating CCR2+CD115+Ly6C+ in the peripheral blood of HFD mice compared with ND controls on day 3 post-injury, suggesting that obesity increases production and/or mobilization of these cells in bone marrow." (PMID 38474365, 2024). "Coincidentally, data from mouse models confirm that when fed a high-fat diet, mice lacking CCR2 eat less and are less likely to become obese, and CCR2 antagonist therapy lowers inflammatory aspects of obesity, such as macrophage infiltration in adipose tissue." (PMID 37153575, 2023). "CB2R agonists have been shown to ameliorate albuminuria, reduce C-C motif Chemokine Receptor-2 (CCR2) expression in the renal cortex and cultured podocytes, lower mesangial expansion and decrease MCP1 expression in animal models of diabetes and obesity." (PMID 35203616, 2022). "Indeed, adipocytes secrete the primary ligand for C-C motif chemokine receptor 2 (CCR2; expressed on circulating monocytes), the monocyte chemoattractant CCL2 (MCP-1), and its expression increases in obesity." (PMID 34613819, 2021). "In addition, HFD-induced ATM accumulation in monocytes is dependent on CCR2, whereas AT-DC accumulation is less dependent on CCR2 but more dependent on CCR7, suggesting that AT-DCs play an independent role in VAT inflammation during obesity." (PMID 34421909, 2021). "Since the classical monocytes have upregulated chemokines such as CCR2 and CCR5 it is likely that this contributes to more activated tissue macrophages in the children with obesity in this cohort, and why these same children with obesity have higher insulin levels and HOMA-IR." (PMID 32528415, 2020). "Our results indicated that WAT CCR2 may play a vital role in macrophage infiltration and the inflammatory response during the development of insulin resistance in HFD-induced obesity." (PMID 29967759, 2018). "Thus, we studied the role of CCR2 in SAT and VAT during the development of insulin resistance related to obesity." (PMID 29967759, 2018). "Besides the CCR2 and CCR5 ligands, a recent study showed that during obesity CXCL12 recruits macrophages via CXCR4 to the adipose tissue." (PMID 30245686, 2018). "Also, a positive correlation has been established with the degree of obesity and the blood concentration of MCP-1, which induces the infiltration of macrophage into WAT via C-C chemokine receptor-2 (CCR2) and also plays a role in inflammatory changes." (PMID 28168013, 2017). "Moreover, recently it has been reported that macrophage-targeted delivery of small interference RNA against CCR2 inhibited ATM recruitment and accumulation in adipose tissue, thus reducing the downstream effects of obesity-induced inflammation." (PMID 28115795, 2017). "Strategies to suppress the CCL2/CCR2 signal may only partially inhibit ATM accumulation and insulin resistance at the late stage of obesity." (PMID 27031964, 2016). "However, no data on the role of CCR2 in obesity-induced hypersensitivity have been reported, and exploratory studies in animal models are needed to address this topic." (PMID 39457105, 2024). "Studies in CCR2 KO mice have shown that the absence of CCR2 leads to an increase in eosinophil numbers, macrophage activation, and altered cytokine expression within adipose tissue, particularly under conditions of obesity induced by a high-fat diet." (PMID 39201480, 2024). "Moreover, flow cytometry analysis confirmed the in vivo imaging data, demonstrating that obesity increased accumulation of pro-inflammatory CCR2+monocytes/macrophages (CCR2+Ly6C+) but not mature macrophages (CCR2+Ly6C-F4/80+) in wounds." (PMID 38474365, 2024).